PLRG1 (pleiotropic regulator 1)
Description:
Involved in pre-mRNA splicing as component of the spliceosome. Component of the PRP19-CDC5L complex that forms an integral part of the spliceosome and is required for activating pre-mRNA splicing. As a component of the minor spliceosome, involved in the splicing of U12-type introns in pre-mRNAs (Probable).
Synonyms: PRL1; Prp46; PRPF46; Cwc1; TANGO4
Tractability: Small molecule: a structure with a bound ligand is known. PROTAC: ubiquitination databases record sites on it; its protein half-life has been measured.
Gene: Protein-coding gene on chromosome 4 (154,535,005 to 154,550,403, reverse strand). Ensembl gene ENSG00000171566.
Subcellular location: Nucleus; Nucleus speckle
Subcellular location (Human Protein Atlas): Nuclear speckles; Nucleoplasm; Nuclear membrane; Nucleoli fibrillar center
Pathways (Reactome):
Disease: Dengue Virus-Host Interactions
Metabolism of RNA: mRNA Splicing - Major Pathway
Gene Ontology:
Molecular function: protein binding
Biological process: mRNA splicing, via spliceosome
Cellular component: catalytic step 2 spliceosome; DNA replication factor A complex; fibrillar center; nuclear membrane; nuclear speck; nucleoplasm; nucleus; post-mRNA release spliceosomal complex; post-spliceosomal complex; Prp19 complex; spliceosomal complex; U12-type catalytic step 2 spliceosome; U2-type catalytic step 1 spliceosome; U2-type catalytic step 2 spliceosome
Genetic constraint (gnomAD): Loss-of-function variants: 4 observed, 16.93 expected, observed/expected ratio (o/e) 0.24, 90% interval 0.12 to 0.54. The upper end of that interval is the gene's LOEUF score, 0.54, which puts it in group 2 of 6, group 1 being the genes least tolerant of losing a copy. Missense variants: 93 observed, 184.49 expected, observed/expected ratio (o/e) 0.5, 90% interval 0.43 to 0.6. Synonymous variants: 66 observed, 66.39 expected, observed/expected ratio (o/e) 0.99, 90% interval 0.81 to 1.22.
Homologues: Orthologues: chimpanzee PLRG1 (99% identical), macaque PLRG1 (99% identical), rabbit PLRG1 (96% identical), guinea pig PLRG1 (96% identical), dog PLRG1 (96% identical), mouse Plrg1 (96% identical), rat Plrg1 (96% identical), tropical clawed frog plrg1 (85% identical), zebrafish plrg1 (78% identical), Drosophila melanogaster Tango4 (60% identical), Caenorhabditis elegans plrg-1 (53% identical).
Diseases named in the same sentence as PLRG1 in open-access papers:
PLRG1 is named in the same sentence as 14 diseases in open-access papers, as found by Europe PMC text mining. Sharing a sentence is not in itself a finding about the gene and the disease. The quoted sentences say what the papers report.
gastric cancer (2 papers, 2022). A primary or metastatic malignant neoplasm involving the stomach. "Interestingly, some upregulated genes found in RNA processing (MAGOH, SCAF11 and PLRG1) have been shown to play a role in tumorigenesis and cancer aggressiveness in glioma, liver, and gastric cancers." (PMID 36010871, 2022). "MNX1-AS1, PLRG1, and SNX5 gene expression levels were found to be higher in 70 primary gastric cancer samples after genome-wide expression profiling." (PMID 35831348, 2022). "Specifically, 8 genes NRP1, MNX1, SSRP1, PRDX2, PLRG1, LGALS4, SNX5 and FXYD3) which are highly expressed in stomach cancer were significantly down-regulated in PRU treated samples." (PMID 35831348, 2022). "Validation of the RIPK genes through GEPIA identified 8 genes (NRP1, MNX1, SSRP1, PRDX2, PLRG1, LGALS4, SNX5 and FXYD3) which are highly expressed in stomach cancer were significantly down-regulated in PRU treated samples." (PMID 35831348, 2022). "Specifically, 8 genes (NRP1, MNX1AS1, SSRP1, PRDX2, PLRG1, LGALS4, SNX5 and FXYD3) were found to be highly expressed in stomach cancer tissues compared to normal tissues." (PMID 35831348, 2022).
dilated cardiomyopathy (1 paper, 2012). Cardiomyopathy which is characterized by dilation and contractile dysfunction of the left and right ventricles. "And fifth, in mice, cardio-specific inactivation of Plrg1 induces massive dilatation and atrophy of both cardiac ventricles characteristic of severe dilated cardiomyopathy, further leading to post-natal lethality." (PMID 22859963, 2012).
fibrosis (1 paper, 2020). the formation of excess fibrous connective tissue in an organ or tissue in a reparative or reactive process. "Fibrosis in renal tubular interstitium reflected chronic injury and loss of function of kidney, which was also consistent with the association between pLRG1 and renal function above." (PMID 32252660, 2020).
leukemia (1 paper, 2019). A malignant (clonal) hematologic disorder, involving hematopoietic stem cells and characterized by the presence of primitive or atypical myeloid or lymphoid cells in the bone marrow and the blood. "To further explore the clinical significance of these hub genes (SUGP1, DHX16, FUS, HNRNPR, DHX15, NAA38, SKIV2L2, and PLRG1), we used a series of online tools to evaluate the clinical expression of these hub genes in leukemia." (PMID 31766457, 2019). "In our study, nanosecond pulsed electric fields induced obvious PLRG1 gene expression increase, indicating that nanosecond pulsed electric fields may affect the cell proliferation of leukemia cells." (PMID 31766457, 2019).
lung adenocarcinoma (1 paper, 2021). A carcinoma that arises from the lung and is characterized by the presence of malignant glandular epithelial cells. "In addition, we analyzed USP42 and PLRG1 expression in the TCGA dataset and found significant upregulation of USP42 and PLRG1 in lung adenocarcinoma and squamous carcinoma." (PMID 33731873, 2021).
lung carcinoma (1 paper, 2021). "USP42 governs the phase separation of the spliceosome component PLRG1 to regulate a range of mRNA splicing events that are linked to diverse cellular functions and the clinical prognosis of lung cancer patients." (PMID 33731873, 2021). "To explore the clinical relevance of USP42 and PLRG1 expression in lung cancer, we analyzed the overall survival of cancer patients using datasets from GSE11969 and GSE31210." (PMID 33731873, 2021). "Strikingly, increased expression of USP42 or PLRG1 negatively correlated with patient survival, thus indicating a tumour-promoting role for both USP42 and PLRG1 in human lung cancer." (PMID 33731873, 2021).
non-small cell lung carcinoma (1 paper, 2021). A group of at least three distinct histological types of lung cancer, including non-small cell squamous cell carcinoma, adenocarcinoma, and large cell carcinoma. "Finally, USP42 expression is strongly correlated with that of PLRG1 in non-small-cell lung cancer samples and predicts adverse prognosis in overall survival." (PMID 33731873, 2021).
cancer (3 papers, 2021 to 2022). A tumor composed of atypical neoplastic, often pleomorphic cells that invade other tissues. "Functionally, USP42 downregulation deregulates multiple mRNA splicing events and leads to deterred cancer cell growth, which is consistent with the impact of PLRG1 repression." (PMID 33731873, 2021).
tumor (2 papers, 2019 to 2021). "It is worth noting that SUGP1 and PLRG1 were not available in the Oncomine databases, hinting that these two genes may have little to do with tumor cell proliferation." (PMID 31766457, 2019).
renal disease (1 paper, 2020). "We found pLRG1 was elevated in LN patients compared to HC and might be a good indicator of renal function and renal disease activity of LN." (PMID 32252660, 2020). "Meanwhile, pLRG1 was a biomarker of renal disease activity of LN." (PMID 32252660, 2020). "pLRG1 was elevated in patients with high renal disease activity and LRG1 could be induced by some inflammatory cytokines." (PMID 32252660, 2020).
PLRG1 also shares sentences with these, for which no sentence is quoted: endometrioid endometrial adenocarcinoma (1 paper); glioma (1); squamous carcinoma (1); stomach cancer (1).